CD70 (CD70 molecule)
Diseases named in the same sentence as CD70 in open-access papers (continued):
Sharing a sentence is not in itself a finding about the gene and the disease.
tumor (continued). "Co-stimulatory signals to CD8 T cells can also be transferred via CD27-CD70 interactions, and Tregs have been shown to inhibit anti-tumor CTLs, in part by an enhanced CD70 sensitivity." (PMID 31333674, 2019). "Specifically, we genetically fused scFvs specific for the tumor-associated antigens CD19, CD20, and CD70 to the C-terminus of the C4-IgG1(N297A) heavy chain." (PMID 30833543, 2019). "The staining of CD70 in various tumour types was localised either on the membrane or in the cytoplasm." (PMID 31652572, 2019). "A similar observation was also obtained from our preclinical study using a syngeneic GBM model, in which 70% of the inoculated tumor was positive for CD70, and nearly 40% of the animals were cured by the murine CD70CAR T cells." (PMID 31488817, 2019). "It has been shown to play an important role in recruiting immunosuppressive myeloid cells to the tumor microenvironment and CD70-CAR T-cells have demonstrated remarkable efficacy in patient xenograft and syngeneic murine tumor models." (PMID 30740109, 2018). "Although some studies suggested that CD70 is regulated by epigenetic mechanisms, how it is governed in response to the alterations in the tumor microenvironment has yet to be determined." (PMID 29721188, 2018). "CD27 molecules expressed on the surface of NK cells can bind to CD70 molecules on the surface of tumor cells to transduce activation signals and enhance the expression and release of perforin and granzyme B and promote the killing activity of NK cells." (PMID 29643992, 2018). "In contrast, we have previously revealed constitutive overexpression of CD70 on malignant cells in 16% of NSCLC tumor specimens." (PMID 29088768, 2017). "The in vivo anti-tumor activity of the CD70-TTC was assessed in the subcutaneous 786-O xenograft mouse model with lesion dimensions averaging 150 mm3." (PMID 28915592, 2017). "All CD70-TTC dose groups demonstrated statistically significant tumor growth inhibition when compared to the vehicle control group." (PMID 28915592, 2017). "ARGX-110, a glyco-engineered fully humanized monoclonal antibody was shown to induce potent ADCC upon binding to CD70 positive tumor cells." (PMID 28915592, 2017). "In the present work, we describe the generation of a CD70-TTC that utilizes the benefits of the high linear energy transfer of alpha particle emitters delivered to the tumor by an antibody." (PMID 28915592, 2017). "Biodistribution of the CD70-TTC was performed in 786-O tumor-bearing athymic mice bearing lesions with an average dimension of 200-300 mm3." (PMID 28915592, 2017). "Scoring was performed by one pathologist, positive staining was assigned when tumor cells of any intensity and any CD70 distribution (membranous, cytoplasmic) showed specific CD70 staining." (PMID 29088768, 2017). "In contrast to the negligible expression of the immunomodulating protein CD70 in normal tissue, we have demonstrated constitutive overexpression of CD70 on tumor cells in a subset of primary non-small cell lung cancer (NSCLC) biopsies." (PMID 29088768, 2017). "Whereas anti-CD27 antibodies, such as Varilumab (CDX-1127), just boost innate and adaptive antitumor responses, anti-CD70 antibodies also target tumor cells inducing direct cell killing." (PMID 29387053, 2017). "Next, the CDDP-induced expression of CD70 was examined in vivo using A549 tumor-bearing CD1 nude mice to verify the expression upon CDDP-treatment and the effects of multiple treatment regimens." (PMID 29088768, 2017). "Expression of the TNF family member CD70 is normally restricted to activated T and B-cells but it is activated in a wide variety of tumors where it promotes tumor cell expansion and survival." (PMID 27144453, 2016). "Example biomarkers of interest currently includes cell surface molecules such as PDL1, CD70 and ICOS expression, tumour mutational load by exome sequencing, as well as detailed immune cells analysis by immune profiling or by TCR sequencing." (PMID 27777776, 2016).
tumor (continued). "In agreement with this we have previously demonstrated that CD70-positive murine tumor cells co-expressing CD40L and H-2K(d) generated an enhanced anti-tumor immune response." (PMID 26828592, 2016). "The constitutive overexpression of CD70 on tumor cells and its absence on normal tissue, has led to the development of two different anti-CD70 monoclonal antibodies (mAb), SGN-CD70A and ARGX-110." (PMID 25951351, 2015). "From the 8 patients with CD70+ tumor cells, positivity correlated more frequently with squamous NSCLC (26.7% CD70+) in comparison to adenocarcinoma (9.4% CD70+)." (PMID 25951351, 2015). "In this perspective, chimeric antigen receptor T cells (CD27-CD3ζ) have been reported to kill CD70+ tumor cells and mediate tumor regression in mice." (PMID 25792975, 2015). "On the contrary, co-culture of CD70+ tumor cells and CD27+ immune cells was shown to inhibit alloreactive T cell proliferation and induce T cell apoptosis." (PMID 25792975, 2015). "For example, overexpression of CD70 by tumor cells has been shown to promote T cell dysfunction or apoptosis through CD27 signaling in vitro." (PMID 26500773, 2015). "Of the tumor-primary culture combinations, parental tissue of L2531 (p363) exhibited CD70-expressing cells in focal regions." (PMID 25792975, 2015). "Overall, 55% of samples (23 of 42) were found to contain more than 10% CD70+ TILs in the tumor microenvironment." (PMID 25951351, 2015). "CD70 expression was only detected on primary cultures if these were derived from a tumor specimen containing CD70+ cells, indicating that CD70 expression was not caused by in vitro cell culture." (PMID 25792975, 2015). "Patients with high sCD27 levels and CD70+ tumor cells did show a significantly shorter OS (P-value: 0.000002) and PFS (P-value: 0.002) compared to patients with high sCD27 levels alone (data not shown)." (PMID 25951351, 2015). "Subsequently, the phenotype of CD27+ TILs was investigated in serial cuts of CD70+ and CD70− tumor samples." (PMID 25951351, 2015). "Aside from its role in adaptive immunity, CD70 is expressed on certain solid tumors and reported to be involved in tumor cell escape from immunosurveillance." (PMID 25792975, 2015). "CD70 expression was assessed in tumor biopsies taken both before and after platinum-based chemotherapy and shown to be clearly upregulated after treatment." (PMID 25951351, 2015). "Forced expression of CD70 in a transgenic mouse model provides protection against an otherwise lethal challenge of tumor cells by constitutive activation of the CD27 pathway." (PMID 26500773, 2015). "Noteworthy, of one patient (patient (p) 404) with cultures from consecutive tumors, the culture derived from the local recurrent tumor exhibited equally high CD70 expression as the culture derived from the primary tumor of this patient." (PMID 25792975, 2015). "The rationale for this approach is emphasized by the more efficient T-cell response in human CD70 transgenic mice upon tumor challenge." (PMID 23840967, 2013). "The interaction between anti-CD70 mAb and CD70 on tumor cell surfaces led to prodrug release and activation." (PMID 24093097, 2013). "For instance, the humanized IgG1 antibody SGN-70 eliminated CD70-positive tumor cells leading to tumor regression in disseminated lymphoma and multiple myeloma xenograft models, in this case via typical antibody effector functions, such as ADCC and CDC." (PMID 23840967, 2013). "Its antitumor activity is due to the alkylating action of CC-1065 on adenine, leading to a reduced proliferation of CD70+ tumor cells." (PMID 24093097, 2013). "Although CD70 expression is prevalent in many tumour types, the percentage of CD70-positive cases varies." (PMID 20664585, 2010). "Our studies extend beyond a survey of CD70 in solid tumour specimens by validating the anti-tumour activity of SGN-75 in these indications." (PMID 20664585, 2010). "The targeting of CD70 by SGN-75 is thought to be driven by the delivery of cys-mcMMAF to the tumour." (PMID 20664585, 2010).
tumor (continued). "We proceeded to use 1C1 and 5D12 mAbs as IHC reagents to expand our analysis of CD70 expression in various tumour types." (PMID 20664585, 2010). "The antibodies 1C1 and 5D12 consistently showed sensitive and specific binding to CD70 in FFPE samples of CD70-positive normal human lymphoid tissues and tumours." (PMID 20664585, 2010). "In preclinical studies, we have demonstrated in vitro anti-tumour activity of the anti-CD70 antibody-drug conjugate SGN-75 in CD70+ ovarian and pancreatic cell lines." (PMID 20664585, 2010). "Other tumour types that expressed CD70 also showed heterogeneous staining pattern with lower intensity." (PMID 20664585, 2010). "To describe the variability of expression, we plotted the intensity of CD70 staining against the percentage of tumour cells that stained positive within the biopsy core." (PMID 20664585, 2010). "Both chimeric and humanised anti-CD70 monoclonal antibody (mAb) 1F6 conjugated to a microtubule-disrupting auristatin have been shown to be active in these tumours." (PMID 20664585, 2010). "The effector-function-based activities of h1F6 are retained in the ADC (J McEarchern and C Law, unpublished observations), suggesting that SGN-75 has the potential to mediate anti-tumour activity in CD70+ tumours through multiple mechanisms." (PMID 20664585, 2010). "CD70+ tumour cell lines were used for testing the anti-tumour activity of the anti-CD70 antibody–drug conjugate, SGN-75." (PMID 20664585, 2010). "These tumor cells would therefore be genetically modified to express two co-stimulatory molecules, CD70 and CD80, which are known to induce an anti-tumor response in syngeneic mice." (PMID 15279677, 2004). "Furthermore, the protocol details procedures for evaluating antitumor efficacy using in vitro tumor cell killing assays with RCC cell lines that exhibit varying levels of CD70 expression, thereby modeling different antigen-density scenarios." (PMID 41533507, 2026). "In this study, we found that long-term, low-dose HMA treatment upregulated CD70, NK receptor ligands, and CD1d on AML tumor cells, rendering them more susceptible to chimeric antigen receptor (CAR)-engineered invariant natural killer T (CAR-NKT) cell-mediated cytotoxicity." (PMID 41888396, 2026). "Amidst repeated CD70+ tumor challenges, ADP-520 TRuC T cells showed slower kinetics and reduced co-expression of exhaustion markers, such as PD-1, the receptor for PD-L1, whose intratumoral expression was linked to poor clinical efficacy of gavo-cel TRuC T-cell therapy." (PMID 40519930, 2025). "Targeting those enzymes, which add or remove these modifications, might be beneficial on controlling CD70 expression, enhancing anti-tumor immune responses." (PMID 40565233, 2025). "Tumor cells regulate CD27 expression in the TME by expressing CD70, which promotes immune escape." (PMID 40205178, 2025). "Among the two patients who received R-chemotherapy, one (MC4) gained additional mutations (SELENBP1) in relapse based on pretreatment dominant tumor clones, whereas the other (MC206) acquired mutations (CD70 and ZFP36L1) from a minor and undetected pretreatment tumor clone." (PMID 40876452, 2025). "CD70 is markedly expressed in hematological malignancies, activating signaling pathways via its interaction with CD27, which mediates T cell exhaustion, enhances Treg function, and recruits tumor-associated macrophages." (PMID 41155287, 2025). "CD70’s tumor-selective expression makes it an attractive target." (PMID 40896423, 2025). "These HIT‐T cells exhibited greater antigen sensitivity and enhanced degranulation compared to conventional CAR‐T cells, thereby improving therapeutic efficacy for tumour cells with low CD70 expression and effective tumour growth suppression in preclinical models." (PMID 40629902, 2025). "Therefore, CD70 holds significant clinical value not only in the diagnosis and treatment of CD70‐positive tumours but also as a potential breakthrough for the treatment of immune‐related diseases." (PMID 40629902, 2025).
tumor (continued). "Interestingly, CD70 expression in HNSCC tumor cells is correlated with tumor differentiation and is also found in tumor-associated blasts and endothelial cells." (PMID 40675157, 2025). "Moreover, despite growing evidence that RNA modifications shape immune cell function and tumor immune evasion, their regulatory influence on immune checkpoint molecules such as CD70, CD80, and TIGIT remains largely unexplored." (PMID 40565233, 2025). "ALLO-316 is an allogeneic CAR T-cell therapy derived from healthy donors, engineered to target CD70-expressing tumor cells and CD70-positive host T-cells that may mediate rejection." (PMID 40940995, 2025). "Given that tissue-level expression data of prognostic biomarkers are particularly valuable in this aggressive cancer, our research gives a solid basis for validation and experimental studies in the future to underpin the role of the CD70/CD27 axis in SCLC tumor immunology." (PMID 40205178, 2025). "Based on the strong performance of CD70 CAR-TOAd−GFP cells in the NCG mouse tumor burden model, we established a high tumor burden model by intracranially injecting U251 cells into NCG mice (the mice in the control group had a survival time of about 20 days post-treatment)." (PMID 40474210, 2025). "Given CD70’s role in tumor growth and immune evasion, understanding how RNA modifications affect its expression and function could provide insights into novel therapeutic methods." (PMID 40565233, 2025). "Co‐imaging of CD70 with other tumour markers (e.g., CAIX) could also be explored in the future for a more comprehensive assessment of the tumour microenvironment and disease state." (PMID 40629902, 2025). "Notably, CD70‐targeted therapies hold promise as adjuncts to current therapeutic regimens, particularly in CD70‐positive tumours with limited response or acquired resistance to chemotherapy, immunotherapy, or targeted therapies." (PMID 40629902, 2025). "Thus, vimentin-positive tumor cell clusters show lower levels of CD70-expression indicating that the epithelial phenotype is more associated with checkpoint’s expression." (PMID 40205178, 2025). "Furthermore, immunofluorescence staining confirmed high CD70 expression in MC3Ri tumor cells and its colocalization with CD4.Treg and CD8.Tex cells, particularly in perivascular regions." (PMID 40876452, 2025). "Next-generation approaches integrate safety modules: (i) CRISPR-mediated CD70 knockout to prevent fratricide, (ii) cytokine-secreting armored CARs (e.g., IL-15) to counter immunosuppression, and (iii) logic-gated systems to reduce off-tumor toxicity." (PMID 40896423, 2025). "CD70, signaling through its T-cell costimulatory receptor CD27, engages diverse functions in T-cell immunoregulation, while CD70–CD27 dysregulation has been associated with tumor progression." (PMID 40519930, 2025). "Targeted therapy based on CD70 has shown anti-tumor activity and is in clinical trials." (PMID 39744577, 2025). "This differential expression profile implies that CD70-directed therapies could achieve tumor-specific cytotoxicity with reduced off-target effects." (PMID 40896423, 2025). "Additionally, off-tumor expression of CD70 on activated immune cells raises concerns about immune-mediated toxicities." (PMID 40597436, 2025). "We first utilized five human tumor cell lines exhibiting variable CD70 expression." (PMID 40885188, 2025). "In addition CAR-NK cells target CD70, which targets tumor cells in CRC patients and induces significant specific killing." (PMID 40705122, 2025). "Future research should further investigate the regulatory mechanisms and functional roles of CD70 in diverse stromal and immune cell populations across different tumour microenvironments, thereby providing a more robust foundation for the optimization of CD70‐targeted strategies." (PMID 40629902, 2025). "However, elevated levels of CD70 have been observed in various malignancies, and its overexpression contributes to tumor progression." (PMID 40597436, 2025).